ADORA2A (adenosine A2a receptor)
Diseases named in the same sentence as ADORA2A in open-access papers (continued):
Sharing a sentence is not in itself a finding about the gene and the disease.
prostate carcinoma (9 papers, 2022 to 2026). A carcinoma that arises from epithelial cells of the prostate gland. "In particular, ADORA2A mediates immunosuppression in TME and has been suggested to be associated with prostate cancer prognosis." (PMID 38698344, 2024). "Second, we also reported that in neuroendocrine lung and prostate cancers, the activation of ADORA2A signaling triggers proline synthesis and results in neuroendocrine-like profiling changes." (PMID 39014441, 2024). "Here, we found that a G protein-coupled receptor, ADORA2A, is specifically upregulated during neuroendocrine differentiation, a common form of lineage plasticity in prostate cancer and lung cancer following targeted therapies." (PMID 38099497, 2023). "ADORA2A and CYP24A1 demonstrated therapeutic drug synergies in advanced prostate cancer when targeted in combination with existing treatments, PARP inhibitors and calcitriol, respectively." (PMID 38983753, 2024). "Among these targets, five of them (A2AR/ADORA2A, CSK, CYP24A1, BRDT, and BRAF) have been suggested in recent scientific papers to be related to prostate cancer and all can interact with ligands with known therapeutic advantages against advanced prostate cancer." (PMID 38983753, 2024).
breast tumor (8 papers, 2020 to 2025). "The adaptive immune checkpoints BTNL9 and VTCN1 and the innate immune checkpoints CD200 and SIRPA were downregulated in breast tumor tissues while the metabolic immune checkpoints ADORA2A and TDO2 were upregulated in breast tumor tissues." (PMID 33932112, 2021).
COVID-19 (8 papers, 2020 to 2024). A disease caused by infection with severe acute respiratory syndrome coronavirus 2. "Our data indicate a significant reduction of ADORA2A gene expression in the whole blood of patients critically ill with COVID-19." (PMID 36248842, 2022). "To fill this gap of knowledge, we now investigated if the rs2298383 SNP of ADORA2A, associated with decreased A2AR activity, and the rs208294 SNP of P2RX7, associated with increased P2X7R activity, were linked to the severity of COVID-19." (PMID 38892324, 2024).
Hypertension (8 papers, 2012 to 2024). The presence of chronic increased pressure in the systemic arterial system. "As for the rs2298383 SNP of ADORA2A, differences were observed solely for hypertension in the general and dominant models." (PMID 38892324, 2024).
insomnia (8 papers, 2019 to 2025). A sleep disorder characterized by difficulty in falling asleep and/or remaining asleep. "On the other hand, ADORA2A genetic variations influenced the risk of sleep complaints and insomnia in all caffeine consumers, notably the rs2298383, rs4822492 and rs5751876." (PMID 31817803, 2019). "In our study, it was difficult to analyze the impact of ADORA2A SNPs on insomnia on the three groups of caffeine consumers because only 10.7% of subjects were identified with insomnia." (PMID 31817803, 2019). "The results on the impact of six ADORA2A SNPs on reported insomnia, according to the three groups of caffeine consumers, are not shown because less than 10% of subjects were concerned and the numbers of subjects carrying each of the genotype SNPs in the different caffeine groups were low." (PMID 31817803, 2019).
lung carcinoma (8 papers, 2017 to 2024). "Ablation of Adora2a in genetically engineered mouse models inhibits the development and progression of neuroendocrine prostate and lung cancers, and, intriguingly, prevents the adenocarcinoma-to-neuroendocrine phenotypic transition." (PMID 38099497, 2023). "Of note, mouse models in the current study with prostate epithelial or lung specific–knockout of Adora2a provide solid evidence that Adora2a plays an essential role in driving the development and progression of NE prostate and lung cancer in vivo." (PMID 38099497, 2023). "Elevated ADORA2A expression was a stand-alone indicator of a good overall survival prognosis in lung cancer patients." (PMID 37945707, 2023). "Then, we carefully looked into adenosine-mediated genes and found that the A2AR (ADORA2A) gene is relatively highly upregulated in lung cancer (lung squamous cell carcinoma, LUSC) (arrow)." (PMID 38138098, 2023). "Genetic ablation of Adora2a in NE prostate and lung cancer mouse models suppresses tumor growth and progression." (PMID 38099497, 2023). "ADORA2A deficiency in GEMM in prostate and lung cancer could ablate NEtD process, and pharmacological inhibition blockade with ADORA2A antagonist SCH58261 also exhibited a promising antitumor effect in both NEPC and SCLC." (PMID 39372390, 2024). "Importantly, pharmacological blockade of ADORA2A profoundly represses neuroendocrine prostate and lung cancer growth in vivo." (PMID 38099497, 2023). "ADORA2A is selectively upregulated in NE prostate and lung cancer." (PMID 38099497, 2023). "To verify whether the elevation of ADORA2A was a common phenomenon among NE cancers in the lung, we performed IHC staining on a panel of human lung cancer sections including patient samples from 14 patients with LUAD and 19 patients with SCLC." (PMID 38099497, 2023). "Genetic ablation of Adora2a in GEMMs inhibits the development and progression of NEPC and lung cancer, and, intriguingly, prevents the AD-to-NE phenotypic transition." (PMID 38099497, 2023).
Sepsis (8 papers, 2014 to 2024). Sepsis is defined as life-threatening organ dysfunction caused by a dysregulated host response to infection. "Gene ontology of these 23 common DEGs showed that apoptotic process (TRAF1, TNFRSF9, ADORA2A, ZBTB16), negative regulation of transcription (SAP30, TSC22D3, ETS2, ZBTB16), and inflammatory response (TNFRSF9, CCL3, ADORA2A) are the main biological processes affected by sepsis treatment." (PMID 30086151, 2018).
anxiety disorder (7 papers, 2015 to 2025). A category of psychiatric disorders which are characterized by anxious feelings or fear often accompanied by physical symptoms associated with anxiety. "A recent study enlightened an interplay between the microglial cells alterations and anxiety disorders, regulated by adenosine A2A receptor." (PMID 29599709, 2018). "ADORA2A rs5751876 genotypes TT+TC (dominant model) were significantly associated with a lower risk of non-OCD anxiety disorders (OR 0.46, 95% CI: 0.21–1.0, p = 0.045)." (PMID 26317759, 2015). "The interaction of ADORA2A and DRD2 genes has been reported to be responsible for anxiety disorders in ADHD children and adolescence." (PMID 36211978, 2022).
atrial fibrillation (7 papers, 2013 to 2023). A disorder characterized by an electrocardiographic finding of a supraventricular arrhythmia characterized by the replacement of consistent P waves by rapid oscillations or fibrillatory waves that vary in size, shape and timing and are accompanied by an irregular ventricular response. "Increased adenosine A2A receptor (A2AR) expression and activation underlies a higher incidence of spontaneous calcium release in atrial fibrillation (AF)." (PMID 36901835, 2023). "Occasionally, we also observed atrial fibrillation in adora2a-morphants and embryos developed excessive pericardial effusion and precardial blood congestion as a consequence of the reduced cardiac function." (PMID 23341106, 2013).
glaucoma (7 papers, 2014 to 2022). Increased pressure in the eyeball due to obstruction of the outflow of aqueous humor. "Recently, we demonstrated that antagonists of adenosine A2A receptor (A2AR) control retinal inflammation and afford protection to rat retinal cells in glaucoma models." (PMID 30667095, 2019).
head and neck squamous cell carcinoma (7 papers, 2017 to 2023). A squamous cell carcinoma that arises from any of the following anatomic sites: lip and oral cavity, nasal cavity, paranasal sinuses, pharynx, larynx, and salivary glands. "The adenosine A2A receptor (A2AR) has been associated with advanced pathological grade along with HIF-1α expression in head and neck squamous cell carcinoma (HNSCC)." (PMID 33348579, 2020).
injury (7 papers, 2017 to 2025). Damage inflicted on the body as the direct or indirect result of an external force, with or without disruption of structural continuity. "Studies in mice indicate that HIF-dependent increases in extracellular adenosine production and signaling through the Adora2A or Adora2b adenosine receptor attenuate inflammation or promote alveolar fluid clearance, thereby dampening pulmonary edema during acute lung injury." (PMID 40526427, 2025). "In the present study, the expression of the adenosine A2A receptor was suppressed by intratracheal instillation, whereas PDRN treatment led to its overexpression in LPS-induced lung injury rats." (PMID 28837114, 2017).
myocardial ischemia (7 papers, 2020 to 2025). A disorder of cardiac function caused by insufficient blood flow to the muscle tissue of the heart. "The activation of ADORA2A promotes cell survival by inhibiting apoptosis and autophagy, thereby mitigating myocardial ischemia–reperfusion injury (MIRI), which may be associated with its capacity to activate the cAMP-PKA pathway and the Beclin-1-Bcl-2 complex." (PMID 40286230, 2025). "Taken together, these result demonstrated that activation of adenosine A2a receptor using NECA prior to reperfusion attenuated myocardial ischemia reperfusion injury in the diabetic rats." (PMID 36964482, 2023). "Previous studies revealed that the adenosine A2a receptor regulated autophagy, but the specific mechanism in myocardial ischemia-reperfusion injury was still unclear." (PMID 35571159, 2022). "The adenosine A2a receptor (A2aR) has played a crucial part in cardiac ischemia-reperfusion injury." (PMID 35571159, 2022). "Furthermore, ACE2 was found to interact with Adenosine A2A Receptor (ADORA2A), a receptor involved in regulating vascular tone and myocardial ischemia." (PMID 40142959, 2025).
pulmonary hypertension (7 papers, 2017 to 2023). Increased pressure within the pulmonary circulation due to lung or heart disorder. "ADORA2A is thought to provide a protective effect against the development of pulmonary hypertension, another clinical phenotype that presents in some ROHHAD individuals consequent to recurrent low oxygen due to inadequately managed hypoventilation." (PMID 37234859, 2023).
atherosclerosis (6 papers, 2017 to 2025). A disease characterized by the build-up of fatty material and calcium deposition in the arterial wall resulting in partial or complete occlusion of the arterial lumen. "In addition to its interactions with MMP9 and ADORA2A, ACE2 also showed connections with Apolipoprotein E (APOE), a protein that plays a central role in lipid metabolism and atherosclerosis." (PMID 40142959, 2025).
Autoimmunity (6 papers, 2016 to 2025). The occurrence of an immune reaction against the organism's own cells or tissues. "However, adenosine A2A receptor deletion reverses the inhibition of L. reuteri on autoimmunity induced by Treg-deficiency in SF mice." (PMID 29270168, 2017). "To determine the role of the adenosine A2A receptor in the pathogenesis of autoimmunity in the SF mouse, we bred female (Foxp3sf/+) mice with adora2a gene knockout A2A-/- mice." (PMID 29270168, 2017).
glioblastoma (6 papers, 2019 to 2022). The most malignant astrocytic tumor (WHO grade IV). "Analysis of adenosine receptors showed that expression of ADORA2A/A2AR and ADORA2B/A2BR in glioblastoma and diffuse glioma were moderate compared to that of other cancers, while ADORA1/A1R and ADORA3/A3R were expressed at significantly higher levels in glioblastoma compared to all other tumor types." (PMID 35973991, 2022).
hepatocellular carcinoma (6 papers, 2021 to 2024). A malignant tumor that arises from hepatocytes. "Adenosine produced by CD73 docked to adenosine A2A receptor-activated Rap1 and promoted Akt phosphorylation in hepatocellular carcinoma cells." (PMID 35417854, 2022). "In tumor cells of hepatocellular carcinoma, adenosine produced by CD73 binds to the high-affinity adenosine A2A receptor (A2AR), which then activates Ras-proximate-1 (Rap1)." (PMID 33430239, 2021).
ischemic stroke (6 papers, 2015 to 2025). A stroke disorder caused by obstruction of blood flow to the brain, due to thrombotic (local blood clot formation) or embolic (due to a blood clot or other material traveling from another site) event. "Most of cells involved in wound healing express the adenosine A2A receptor, and this adenosine A2A receptor is locates in several brain regions and modulates the pathophysiological response to ischemic stroke." (PMID 33735236, 2021). "Previously, we identified the human orthologues for a number of rat genes, which expression was changed after ischaemic stroke (Adora2a, Bcl3, Ccl22, Ccr1, Cd14, Gpr6, Gpr88, Rgs9, and other genes)." (PMID 34946819, 2021). "Among the downregulated genes, Gpr88, Rgs9, Enthd1, Olr59, P2ry12, Degs2, Pde10a, Neu2, Adora2a, and Slc22a6 were found to demonstrate significant downregulation in pathological phase of ischemic stroke." (PMID 25861363, 2015).
migraine (6 papers, 2018 to 2024). "Moreover, the adenosine A2A receptor gene haplotype was found to be associated with migraine with aura." (PMID 32631251, 2020). "Future research should also confirm and investigate a role of receptor genes like ADORA2A in migraine and caffeine withdrawal." (PMID 31849829, 2019). "We suggest that the adenosine A1 receptor and adenosine A2A receptor could be potential targets for migraine treatment." (PMID 35382738, 2022). "Indeed, the adenosine A2A receptor subtype is widespread in the areas of the brain that are innervated by dopamine fibers (e.g., striatum, nucleus accumbens, and olfactory tubercle), and modulation of dopamine has previously been shown to mitigate headache and migraine symptoms." (PMID 35103121, 2021).
pulmonary fibrosis (6 papers, 2016 to 2023). Chronic progressive interstitial lung disorder characterized by the replacement of the lung tissue by connective tissue, leading to progressive dyspnea, respiratory failure, or right heart failure. "In this research, we aimed to explore the essential role of adenosine A2a receptor in a BLM-induced pulmonary fibrosis model using the A2aR KO mice, and investigated whether baicalin protected against pulmonary fibrosis via the TGF-β1-induced ERK1/2 signaling pathway." (PMID 27658704, 2016). "Thus, some of the differences in the findings about the roles of ADORA2A and ADORA2B in radiation-induced dermal and pulmonary fibrosis may well be due to the differences in the damage model." (PMID 31623231, 2019).
attention deficit-hyperactivity disorder (5 papers, 2015 to 2024). A disorder characterized by a marked pattern of inattention and/or hyperactivity-impulsivity that is inconsistent with developmental level and clearly interferes with functioning in at least two settings (e.g. at home and at school). "The Adora2a gene’s polymorphism has been found to be linked to the occurrence of central nervous system disorders, including attention-deficit hyperactivity disorder (ADHD) and Tourette’s syndrome." (PMID 37759104, 2024). "The social recognition test (SRT) has been used in studies with caffeine, an adenosine A2A receptor antagonist, in reversing cognitive decline in age-related deficits in olfactory discrimination, Parkinson's disease, and attention deficit hyperactivity disorder (ADHD)." (PMID 26649059, 2015).
cocaine use disorder (5 papers, 2016 to 2021). A substance-related disorder that involves the recurring use of cocaine despite negative consequences. "The adenosine A2A receptor (A2AR)-dopamine D2 receptor (D2R) heteroreceptor complexes and their allosteric receptor-receptor interactions in the ventral striatal-pallidal GABA antireward neurons are of high relevance for understanding cocaine reward and cocaine use disorder." (PMID 33790790, 2021).
coronary artery disease (5 papers, 2019 to 2022). "We searched for the presence in plasma from coronary artery disease (CAD) patients of EV containing the adenosine A2A receptor (A2AR), a signalling receptor associated with myocardial ischaemia and whose expression is related to homocysteine (HCy) metabolism." (PMID 31444994, 2019). "This review focused on the adenosine A2A receptor subtype, circulating adenosine levels, and their relationship with coronary artery disease." (PMID 32727116, 2020).
diffuse large B-cell lymphoma (5 papers, 2020 to 2025). "The synergistic effect was observed when combining adenosine A2A receptor agonists with cAMP-hydrolyzing PDE inhibitors in multiple myeloma and diffuse large B cell lymphoma cell lines, as well as in primary patient samples." (PMID 40535773, 2025). "Another study found a strong synergistic combinatorial effect between adenosine A2A receptor agonists and cAMP‐hydrolyzing PDE inhibitors in MM and diffuse large B‐cell lymphoma cell lines and primary patient samples." (PMID 32749766, 2020).
fibrosis (5 papers, 2013 to 2025). the formation of excess fibrous connective tissue in an organ or tissue in a reparative or reactive process. "The adenosine A2A receptor (A2AR) also controls renal pathologies of various etiologies such as ischemia-reperfusion injury, fibrosis, diabetic nephropathy, and glomerulonephritis." (PMID 36377661, 2022).
Insulin resistance (5 papers, 2020 to 2023). Increased resistance towards insulin, that is, diminished effectiveness of insulin in reducing blood glucose levels. "In fact, it has been reported that endothelial adenosine 2a receptor (which is encoded by Adora2A gene) activation promoted blood–brain barrier (BBB) breakdown in mice with diet-induced insulin resistance, thus, this effect may impinge on the infiltration of peripheral immune cells into the brain." (PMID 34502030, 2021). "Further study showed that Adora2a activation in endothelial cells exacerbated BBB damage and cognitive dysfunction in diet-induced insulin-resistant mice, while mice specifically knockout of endothelial Adora2a protected BBB integrity after suffering from diet-induced insulin resistance." (PMID 36825149, 2023). "From the available literature it is known that caffeine—non-selective adenosine A2A receptor antagonist is able to inhibit various obesity-related abnormalities, including low metabolism, adiposity, dyslipidemia, systemic/tissue inflammation, and insulin resistance." (PMID 32555600, 2020).
multiple sclerosis (5 papers, 2015 to 2021). A progressive autoimmune disorder affecting the central nervous system resulting in demyelination. "Transcripts encoding adenosin A2a receptor (Adora2a) and ermin (Ermn) have been associated with neurodegeneration, multiple sclerosis and epileptic seizures." (PMID 32742258, 2020). "We here report a profound and complex involvement of adenosine A2a receptor signaling in EAE, an animal model of multiple sclerosis." (PMID 26920550, 2016).
myopia (5 papers, 2011 to 2025). "Adora2a−/− mice were shown to develop relative myopia and denser scleral collagen fibers compared to their WT littermates." (PMID 38635876, 2024). "Collagen synthesis and ECM production in tissues are modulated by the adenosine A2a receptor (ADORA2a), prompting studies of its effect on myopia." (PMID 38635876, 2024). "The retinal expression of the adenosine A2a receptor varies during the day, and deletion of the adenosine A2a receptor subtype induces a relative myopia in mice." (PMID 31211778, 2019). "The adenosine A2A receptor (A2AR) modulates collagen synthesis and extracellular matrix production in ocular tissues that contribute to eye growth and the development of myopia." (PMID 22740769, 2011).